RNU1-94P (RNA, U1 small nuclear 94, pseudogene)
Gene: Small nuclear RNA gene on chromosome 20 (31,901,254 to 31,901,426, forward strand). Ensembl gene ENSG00000199497.
Homologues: Orthologues: chimpanzee U1 (87% identical), guinea pig U1 (62% identical), dog U1 (57% identical). Paralogues in human: RNU1-1 (71% identical), RNU1-2 (71% identical), RNU1-27P (71% identical), RNU1-28P (71% identical), RNU1-3 (71% identical), RNU1-4 (71% identical), RNVU1-18 (71% identical), RNVU1-29 (71% identical), RNVU1-7 (71% identical), U1 (71% identical), RNVU1-28 (71% identical), RNU1-11P (70% identical), and 134 more.